CLDN3 (claudin 3)
Diseases named in the same sentence as CLDN3 in open-access papers (continued):
Sharing a sentence is not in itself a finding about the gene and the disease.
infection (continued). "Interestingly, pre-treatment of OE-TLR3(-) cells with IFN-β prior to infection appeared to mildly but significantly increase the synthesis and stability of claudin-3 at the 20hr time point, while substantially bolstering the synthesis and stability of claudin-1 and claudin-2 throughout infection." (PMID 30625140, 2019). "Moreover, the mean fluorescence intensity of claudin-3 was substantially weakened in wild-type CR-infected colon sections, which indicates altered claudin-3 dynamics or degradation during CR infection in vivo, consistent with previous studies in immunocompetent animals." (PMID 31251784, 2019). "Examination of the integrity of the epithelial barrier by staining for claudin-3, revealed multifocal disruptions and epithelial loss of the normally continuous, epithelial barrier in tissues from the chronic stages of infection, but not in tissues from uninfected or early acute animals." (PMID 20808901, 2010). "Our previous studies showed that the mRNA expression levels of tight junctions including claudin-1, claudin-3, claudin-7, and claudin-11 were up-regulated with AKG supplementation after infection with A. hydrophila." (PMID 35720284, 2022). "Claudin-3 (CLDN3), a member of the claudin family, correlates with infection by HIV, simian immunodeficiency virus (SIV), porcine reproductive and respiratory syndrome virus (PRRSV), avian influenza virus subtype H9N2 infection, and so on." (PMID 39459923, 2024). "When S7-A cells were infected with HCV-JFH1-tau Lot B1 with or without a broad CLDN binder, i.e., C-terminal fragment of Clostridium perfringens enterotoxin (C-CPE), which can bind several CLDNs such as CLDN3, CLDN6, CLDN7, and CLDN917,18, infection was completely blocked by C-CPE." (PMID 36424447, 2022). "In contrast, compared with infection groups, AKG supplementation could significantly upregulate the gene expression levels of claudin-1 and claudin-3, and as well as the mRNA level of claudin-7 and claudin-11 (P < 0.05)." (PMID 34220849, 2021). "The results show that the mRNA expression of the cytoplasmic protein ZO-1 and the cell membrane protein Claudin-3 significantly decreased at 5 dpi and 12 dpi, while the mRNA expression of Claudin-3 and ZO-1 significantly increased in the baicalin plus H9N2 AIV infection group (P < 0.01)." (PMID 33294434, 2020). "In addition, a significant cooperative relationship was observed for CLDN-3 and occludin (OCLN) gene expression levels between E. faecium supplementation and NE infection." (PMID 31311959, 2019). "In contrast with results in the worm model, the expression of claudin-3 as another biomarker of the gut epithelial barrier was not significantly affected in the mouse infection model." (PMID 31500368, 2019). "The infection did not negatively affect the CLDN-3 levels in the infected groups with CBD addition." (PMID 39518951, 2024).
adenocarcinoma (7 papers, 2014 to 2024). A common cancer characterized by the presence of malignant glandular cells. "We found that the level of CLDN3 protein was significantly higher in the adenocarcinoma specimens compared with normal tissues (**p<0.01)." (PMID 28160565, 2017). "The epithelial markers E-cadherin, claudin-3 and claudin-4, commonly decreased in human adenocarcinomas are actually up regulated during ovarian carcinogenesis." (PMID 25278811, 2014). "Conversely, NKX2-1 and mucins (MUC1, MUC5B) were more highly expressed in adenocarcinoma, as were ROS1 and CLDN3." (PMID 32381040, 2020).
neurological disorders (5 papers, 2019 to 2025). "In neurological disorders loss of claudin-3 immunostaining is observed at the compromised BBB and blood-cerebrospinal fluid barrier (BCSFB)." (PMID 30659216, 2019). "CLDN-1 and CLDN-3 are the key components of tight junctions in blood brain barrier, and their abnormal function is one of the main reasons for the occurrence and development of nervous system diseases." (PMID 34008771, 2021). "We examined Claudin 1, Claudin 3, Claudin 5, Occludin and ZO-1 in 31 ALS-CP samples compared to 15 non-neurologic disease controls." (PMID 32586411, 2020).
inflammation (2 papers, 2019 to 2023). Aberrant reaction of the microcirculation characterized by movement of fluid and leukocytes from the blood into extravascular tissues. "At the same time, it was found that glutamate could increase the expression of ZO-1, occludin-1, claudin-2, claudin-3, and other tight junction protein, thereby improving the barrier damage caused by intestinal inflammation." (PMID 31772935, 2019).
Intestinal Diseases (2 papers, 2020 to 2021). "Despite the fact that a decreased expression of Claudin-1 has been related with an increased permeability in intestinal disorders, there seems not to be a clear pattern for Claudin-3 expression, which may or may not be affected." (PMID 32098336, 2020).
neurodevelopmental disorder (1 paper, 2024). A behavioral and cognitive disorder with onset during the developmental period that involves impaired or aberrant development of intellectual, motor, or social functions. "The protein is a component of the tight junction complex, and chromosomal microdeletions including the Claudin-3 and Claudin-4 genes are associated with Williams–Beuren syndrome, a neurodevelopmental disorder affecting multiple systems." (PMID 38338705, 2024).
CLDN3 also shares sentences with these, for which no sentence is quoted: inflammatory bowel disease (4 papers); benign prostatic hyperplasia (3); experimental autoimmune encephalomyelitis (3); prostatic adenocarcinoma (3); bacterial infection (2); cervical cancer (2); COVID-19 (2); ductal adenocarcinoma of the pancreas (2); endometrioid adenocarcinoma (2); invasive carcinoma (2); neuroendocrine neoplasm (2); Pancreas Carcinoma (2); acromegaly (1); acute pancreatitis (1); adenoma (1); alcoholic hepatitis (1); allergic reaction (1); Alzheimer disease (1); anaplastic astrocytoma (1); Ascites (1); astrocytoma (1); autism spectrum disorder (1); benign cystadenomas (1); bladder cancer (1); carcinosarcoma (1); celiac disease (1); clear cell carcinomas (1); clear cell renal cell carcinoma (1); Constipation (1); epilepsy (1).
A further 34 diseases each share a sentence with CLDN3 in 1 paper.